CRP (C-reactive protein)
Diseases named in the same sentence as CRP in open-access papers (continued):
Sharing a sentence is not in itself a finding about the gene and the disease.
tumor (continued). "Therefore, it was hypothesized that inflammatory markers, such as CRP, ILs, tumor-infiltrating neutrophils and lymphocytes, and platelets, might be potential indicators for predicting the response of patients with mPC to mFOLFIRINOX." (PMID 35965580, 2022). "However, CRP has been shown to have a tumour-killing activity in both in vivo and in vitro." (PMID 36159866, 2022). "The low baseline CRP level in flare‐responders could be an indirect surrogate for low or absent chronic inflammation caused by the tumor burden." (PMID 34925829, 2021). "Finally, we investigated whether CRP can act as a general enhancer of IgG-mediated cellular destruction, e.g., in mAb-mediated tumor responses." (PMID 33790888, 2021). "Additionally, fever and an increase in C-reactive protein, erythrocyte sedimentation rate, and leukocytes may be seen in cases of hemorrhage or necrosis in the tumor." (PMID 34208030, 2021). "Additionally, CRP levels might reflect an inflammatory response activated as a secondary process in reaction to tumor necrosis or other local tissue damage." (PMID 33685417, 2021). "The high post-CRT LCR in our cohort was largely a reflection of post-CRT maintenance of TLC with a small, but insignificant, increase in CRP level, and it might therefore be indicative of strong anti-tumor immunity and a mild pro-inflammatory effect on the microenvironment." (PMID 34229704, 2021). "A later report, however, did state that anti-tumor activity elicited by CRP in liposomes could be abrogated by treating peritoneal exudate cells with anti-Thy 1.2 (reacting with a marker on T-lymphocytes) or anti-asialo Gm1 (reacting with a marker on NK cells) and complement." (PMID 34552600, 2021). "Furthermore, we also studied whether CRP can be used to amplify tumor cell destruction by monoclonal antibodies (mAbs)." (PMID 33790888, 2021). "Altogether, we provide for the first time evidence for the involvement of specific CRP-FcγR interactions in the exacerbation of in vitro IgG-mediated cellular destruction; a trait that should be further evaluated as potential therapeutic target e.g., for tumor eradication." (PMID 33790888, 2021). "Theoretically, high CRP level may be due to the production of cytokines from tumor cells." (PMID 34221991, 2021). "Our results suggest that tumor levels of CRP may not be linked to metabolic dysregulation, or that the influence of CRP on metabolism may be different from other pro-inflammatory cytokines." (PMID 33235296, 2020). "We hypothesized that: CRP could be associated with tumor immune contexture (TIC) in never-smokers and both these two parameters may improve their prognosis." (PMID 32646072, 2020). "Furthermore, it is demonstrated that elevated CRP influences tumor progression." (PMID 33351844, 2020). "Thus, an increase in CRP may represent elevated levels of pro-inflammatory cytokines that contribute to a microenvironment supporting tumor angiogenesis, proliferation, growth and metastases." (PMID 32182693, 2020). "Second, CRP might be an indicator of the immune response to tumor antigens." (PMID 33059654, 2020). "Moreover, inflammatory signaling from the developing tumor could also act systemically to promote acute phase protein production (e.g., hepatic CRP) and provide a positive feedback loop to potentiate this pro-metastatic inflammatory environment." (PMID 33324413, 2020). "Finally, Cyr61 may be involved in the process of tumor metastasis and progression by producing IL-6 and CRP in the EOC inflammatory microenvironment." (PMID 31766991, 2019). "Since CRP synchronously rises and falls with initiation and termination of the immune response, we determined the start of the cycle as the “most favourable” day of the immune cycle “to release tumor antigen” by SBRT-PATHY, while the first day(s) of CRP fall as the “least favourable”." (PMID 31801549, 2019). "CRP was not clearly associated with other histotypes or with low malignant potential tumours." (PMID 31390370, 2019).
tumor (continued). "Furthermore, the positive predictive value (PPV) for CXCL-8 levels was higher than that for SCC-Ag, but lower than that for CRP and CEA, while the diagnostic accuracy of CXCL-8 was marginally lower than that of CRP, but higher than that of the classical tumor markers." (PMID 30820705, 2019). "Our finding revealed that tumor regression was significantly associated with the density of CD8+ TILs in the intraepithelial, the presence of ITB, the combination of NLR and CRP (NLR-CRP) value, and the combination of CD8+ intraepithelial TIL (iTIL) density and ITB presence." (PMID 30867256, 2019). "LDH and CRP have obvious advantages in judging whether the tumour has progressed compared with PCT." (PMID 30976022, 2019). "CRP may also predict post-surgical tumor recurrence therapeutic response and toxicity." (PMID 30138391, 2018). "Tumour cells increase CRP expression by producing inflammatory proteins, including CRP or by enhancing the role of inflammatory cytokines such as IL-6 and IL-8, which could indirectly increase the CRP level." (PMID 29890986, 2018). "First, tumor growth and invasion could promote inflammation and hence increase CRP levels." (PMID 29228679, 2017). "Second, CRP could represent a modulator of the immunological system of the host to tumor antigens." (PMID 29228679, 2017). "In addition, serum measurement of both CRP and albumin is less expensive than tumor markers." (PMID 28644836, 2017). "Elevated serum CRP levels are associated with poor prognosis independent of tumour stage." (PMID 28384249, 2017). "Advanced tumor status (p < 0.001), tumor stage (p < 0.001), skin invasion (p < 0.001), bone invasion (p < 0.001), and tumor depth ≥10 mm (p < 0.001) and advanced pathologic nodal status (p = 0.006) and lymphatic invasion (p = 0.068) were significantly correlated with CRP elevation (CRP ≥ 5.0 mg/L)." (PMID 28209200, 2017). "However, ALP, LDH and CRP (which could be used as tumour-burden parameters) each was a significant predictor of OS in the univariate analysis." (PMID 29262549, 2017). "A third factor, for example inflammation, could increase both CRP level and tumor malignancy." (PMID 27733196, 2016). "MDT and CRP might simply reflect tumor burden or disease progression, in parallel with rising LDH." (PMID 27764805, 2016). "Notably, there are evidence that the inflammatory field effect, reflected by elevated CRP, may be directly involved in tumor progression." (PMID 27733196, 2016). "First, tumor progression may induce tissue inflammation leading to increased CRP serum levels." (PMID 26248232, 2015). "Interestingly, an association between median CRP serum levels and tumor size but not between median CRP and other clinico-pathological parameters was observed." (PMID 26248232, 2015). "CRP is secreted by hepatocytes in response to the inflammatory cytokines produced by the tumor microenvironment, and CRP can enter the tumor microenvironment through the circulation, where it binds to a variety of autologous and extrinsic ligands and plays a key role in the clearance of tumor cells." (PMID 26264146, 2015). "Another possibility is that an elevated CRP might reflect an immune response to tumor antigens." (PMID 26715527, 2015). "Additionally, some tumor cells could also secret CRP and that may contribute to the serum CRP level." (PMID 26235332, 2015). "Interestingly, we observed an association of elevated CRP serum levels and tumor size but not with other investigated risk factors for ULMS." (PMID 26248232, 2015). "Moreover, CRP may contribute to the establishment of a favorable tumor microenvironment by promoting angiogenesis, by inhibiting the destructive activation of complement, and by inducing proinflammatory cytokines from immune and endothelial cells." (PMID 25025473, 2014).
tumor (continued). "Interestingly, we have recently found that the promoter of CRP is specifically mutated at the SNP position (rs3091244) 286 bp upstream the transcription start site in 109 out of 453 tumor samples but not in the matched normal controls." (PMID 25025473, 2014). "In addition, the chronic elevation of CRP observed in obese subjects may potentiate leptin resistance, contributing to the carcinogenesis, tumor progression and poor outcomes of tumor patients." (PMID 24800842, 2014). "In the present study, a ‘post-embolization syndrome’ consisting of fever, abdominal pain, nausea, vomiting and elevated AST, ALT and CRP levels occurred in almost all patients, which may have been due to the massive necrosis of the tumor, although these symptoms were minimal and transient." (PMID 24137424, 2013). "Therefore, an elevated CRP might indicate tumours capable of producing significant amounts of proinflammatory cytokines, in particular interleukin-6." (PMID 23497335, 2013). "Interestingly, neither neopterin nor CRP concentrations were associated with tumor stage in our population." (PMID 22615854, 2012). "In the present study, elevated CRP levels were indeed associated with larger tumour size, presence of distant metastases, and lower tumour grade (although CRP was not linearly associated with tumour grade), and these prognostic factors were associated with poor prognosis." (PMID 21639875, 2011). "Thus, an important question that arose during this study was whether patients with higher serum CRP (i.e., ⩾30 mg l–1) had been given an insufficient siltuximab dose to suppress their IL-6 levels adequately to achieve a tumour response." (PMID 20808314, 2010). "Thus, both the extent of tumor progression, as well as the prediction of responsiveness to chemotherapy may well be inferred through CRP measurements." (PMID 19341447, 2009). "However, resection of the primary tumour did not appear to be associated with significant normalisation of circulating concentrations of C-reactive protein, interleukin-6 or interleukin-10." (PMID 17003778, 2006). "Also, that an elevated C-reactive protein identifies those patients with T-lymphocyte impairment or patients with a proangiogenic environment allowing unrestrained tumour growth and dissemination." (PMID 16523196, 2006). "We investigated whether preoperative levels of serum C-reactive protein (CRP) and its correlation with tumour clinicopathological findings adds prognostic information beyond the time of diagnosis in patients with myeloma bone disease (MM) to facilitate the surgical decision-making process." (PMID 16969356, 2006). "On multivariate analysis, tumour size (hazard ratio (HR) 2.10, 95% confidence interval (CI) 1.20–3.68, P=0.009), vascular invasion (HR 2.58, 95% CI 1.48–4.50, P<0.001) and postoperative C-reactive protein (HR 2.00, 95% CI 1.14–3.52, P=0.015) retained independent significance." (PMID 15597096, 2005). "High tumor burden; rapid CAR T‐cell expansion; elevated baseline CRP/ferritin; CD28 costimulation; high baseline inflammatory state." (PMID 41207679, 2026). "The clinical picture was consistent with a tumor-induced CRS, evidenced by markedly elevated interleukin-6 (IL-6) and C-reactive protein (CRP)." (PMID 42164115, 2026). "Secondary outcomes assessed operative time, wound complications, postoperative ileus, systemic inflammatory response (C-reactive protein (CRP) and white cell count (WCC)), length of stay, and oncologic adequacy (lymph node harvest, tumour staging)." (PMID 42037851, 2026). "Key predictors identified through univariate and multivariate Cox regression, time-dependent ROC, and LASSO analyses were the lymphocyte-to-C-reactive protein ratio (LCR) and tumor-node-metastasis (TNM) staging." (PMID 41720486, 2026). "Compared with PBS-pretreated mice and DMSO-pretreated tumor-bearing mice, UBCS039-pretreated mice presented increased C-reactive protein (CRP) levels." (PMID 41530841, 2026).
tumor (continued). "In the univariate analysis, several variables were predictive of overall survival (OS), including NLR, PLR, MLR, SII, PIV, CRP, LDH, albumin, tumor size, and Eastern Cooperative Oncology Group Performance Status (ECOG PS)." (PMID 39851955, 2025). "Combining CRP with other biomarkers, such as thymidine kinase 1 (TK1), can enhance the sensitivity for early tumor detection." (PMID 40351765, 2025). "In our cohort, both scores demonstrated significant correlations with CRP, albumin, CEA, CA19-9, and lymphocyte levels, highlighting their ability to reflect systemic inflammation, nutritional status, and tumor burden." (PMID 41517561, 2025). "Clinical data including sex, age, histology, ECOG-PS, tumor stage, smoking status, presence, and site of metastases, LDH, CRP, NLR ratio were collected." (PMID 41374930, 2025). "The integration of AFP and CRP into the CRAFITY score provides a mechanistically informed and clinically accessible framework that captures both tumor-intrinsic characteristics and systemic host immune status." (PMID 41358154, 2025). "Our study’s most notable and unique finding is the observation that URC exhibits higher levels of inflammatory markers (CRP, WBC, neutrophils, and platelets), whereas MLRC demonstrates more frequent LVI, PNI, and tumor budding." (PMID 40277783, 2025). "Elevated systemic CRP levels activate pro-tumorigenic signaling cascades, including NF-κB and MAPK pathways, inducing tumor cells to secrete proinflammatory cytokines, such as IL-6 and TNF-α." (PMID 40563367, 2025). "The diagnostic sensitivity of ADAM15 (38%) was lower than for the classical tumor markers (CA 19-9—52%, CEA—58%) and CRP (65%)." (PMID 40725774, 2025). "The area under the ROC curve (AUC) for ADAM15 (0.5070, p > 0.05) was lower than for the classical tumor markers (CA19-9—0.5617, p > 0.05; CEA—0.7519, p < 0.001) and the marker of inflammation (CRP—0.8220, p < 0.001) in the diagnosis of CRC." (PMID 40725774, 2025). "RAR was positively correlated with C-reactive protein (CRP; r = 0.450), TBIL (r = 0.460), Child-Pugh scores (r = 0.706), and maximum tumour diameter (r = 0.312), but negatively correlated with LYM (r = -0.388) (all p < 0.0001)." (PMID 39781529, 2025). "Tumor marker levels, as well as the WBC and CRP levels and the size of the endometrioma, were evaluated." (PMID 40429382, 2025). "Saliva was collected strictly before the start of treatment, and the content of ten tumor markers was determined by ELISA: EGFR2, CA15-3, CA27.29, MCA, CEA, CA125, CA19-9, CYFRA 21-1, ferritin, and CRP." (PMID 40699615, 2025). "CRP and LDH consistently emerged as the dominant predictors, supporting their biological relevance as markers of systemic inflammation and tumor metabolic activity." (PMID 41590501, 2025). "Significantly increased baseline level of CRP and LDH in the patients with subsequent brain metastases seem consistent with putative inflammatory/immune-mediated background for dissemination of neoplasm." (PMID 40496607, 2025). "According to the SHAP summary plot, the top 10 features with the highest impact on model output were identified as follows: primary tumor localization, ferritin, CA19-9, CRP, uric acid, TSH, triglyceride, total protein, LDL, and platelet (plt)." (PMID 41301066, 2025). "The mechanistic basis lies in CRP’s role in promoting myeloid-derived suppressor cell (MDSC) expansion and PD-L1 upregulation, while lymphocytopenia limits CD8+ T-cell-mediated tumor control." (PMID 41451214, 2025). "Elevated levels of CRP and LDH pretreatment correlate with poor overall survival in cervical cancer, with tumor burden and unfavorable outcomes in pediatric Ewing sarcoma, and serve as independent prognostic factors in primary CNS lymphoma." (PMID 41614767, 2025).
tumor (continued). "The analysis of factors affecting microbiota-brain axis relationships through regression methods showed that CRP and IL-6 and TNF-α inflammatory markers and tumor size and disease stage and hospital stay duration had positive effects." (PMID 41451009, 2025). "The model included the four tumor markers (CEA, CA19-9, CA72-4, AFP), the inflammatory markers (CRP, ESR, fibrinogen), and the AJCC stage (treated as an ordinal variable from I to IV)." (PMID 40299527, 2025). "We evaluated a comprehensive set of clinical and biological endpoints, including patient demographics, tumor histology, molecular and genomic profiles, laboratory biomarkers (such as LDH, CRP, and NLR), and patterns of disease progression." (PMID 41374930, 2025). "While Child-Pugh and BCLC remain standard tools for assessing liver function and tumor burden, respectively, the CRAFITY score provides complementary information by integrating systemic inflammation (via CRP) and liver function reserve (via AFP)." (PMID 41358154, 2025). "LASSO regression was used to identify key prognostic factors, including Age, HBV, WBC, CRP, HSP90α, Child-Pugh classification, ALBI, Tumor number, PVTT, M status, and BCLC stage." (PMID 41458972, 2025). "Evaluation including hematology (FBC and differential), biochemistry (iron studies, vitamins, CRP, LFT, VBG, U&E), coagulation profile, and tumor markers." (PMID 40918821, 2025). "Univariate analysis showed that tumor number (p = 0.0001), microvascular invasion (p = 0.014), extrahepatic metastasis (p = 0.002), AST (p = 0.034), CRP (p = 0.003), BCLC stage C (p = 0.038), and serum GDF15 (p = 0.009) were significantly associated with OS." (PMID 40677718, 2025). "In our investigation, we reported that serum ADAM15 concentrations were higher in CRC patients compared to healthy controls, similar to the classical tumor markers and CRP; however, significant differences were only observed for CEA and CRP." (PMID 40725774, 2025). "According to the results of multivariate Cox regression analysis, it was observed that age, mean follow-up, neutrophil, albumin, CRP, CEA levels, and tumor characteristics (T-stage, N-stage, lymphovascular invasion) were all associated with survival outcomes." (PMID 40797479, 2025). "Low Alb levels are often accompanied by elevated C-reactive protein (CRP) or lactate dehydrogenase (LDH) levels, suggesting systemic inflammation or increased tumor activity." (PMID 41340164, 2025). "Tumor stage, serum biomarkers (CEA, CA 19-9, LDH, and CRP), carotid index (Doppler ultrasound), and neuroimaging (MRI) were recorded." (PMID 41157276, 2025). "Lower neutrophil-to-lymphocyte ratio (NLR) and C-reactive protein (CRP) levels also correlated with improved outcomes, as did smaller tumor sizes (≤5.0 cm)." (PMID 40308490, 2025). "Among the most promising biomarkers, the overexpression of complement component C9 (C9), C-reactive protein, and leucine-rich α-2-glycoprotein (LRG1) is strongly correlated with GBM tumor burden and progression." (PMID 40628732, 2025). "C-reactive protein (CRP) is an acute-phase protein produced in the liver, which can promote tumor cell invasion, angiogenesis, and metastasis in the inflammatory milieu." (PMID 40416620, 2025). "Preoperative levels of CRP, mean platelet volume (MPV), and tumor markers CA 125, CA 19-9, CA 15-3, and CEA, as well as postoperative MPV and neutrophil-to-lymphocyte ratio (NLR), were compared." (PMID 40429382, 2025). "In our study, lower pre-treatment N/CRP ratio and CALLY index were found to be the determining factors in the non-complete treatment response group, with an increase in final tumor diameter, vascular invasion, metastasis, and mortality." (PMID 40181742, 2025). "There were statistically significant differences in ECV, CRP, IL-6, NEU, and the status of other anti-tumor treatments between the two groups (P < 0.05)." (PMID 41199834, 2025).